IL32 (interleukin 32)
Diseases named in the same sentence as IL32 in open-access papers (continued):
Sharing a sentence is not in itself a finding about the gene and the disease.
ovarian carcinoma (5 papers, 2012 to 2025). A malignant neoplasm originating from the surface ovarian epithelium. "High Mobility Group Box 1 (HMGB1) was identified as a key ligand expressed in ovarian cancer cells influencing the IL32 expression in terminally exhausted CD8 + T cells." (PMID 41240232, 2025). "Examples include VCAN, VIM and IL32, mediators of cell motility and invasion when upregulated in ovarian cancers, HNSCCs and metastatic CRCs, respectively." (PMID 29228717, 2017). "The levels of IL-32 protein and mRNA were examined in three different human ovarian cancer cell lines: IGROV1, SKOV3, and OVCAR8 cells." (PMID 29050245, 2017). "In this study, we showed that EVs from ovarian cancer cells upregulated genes related to the inflammatory response, including immune cell–attracting cytokines (CCL2, CCL3/L1, CCL15, CCL18, and CCL20), interleukins (IL1B and IL32), and cell–cell adhesion transcripts (VCAM1 and ICAM1)." (PMID 40689422, 2025).
pulmonary arterial hypertension (5 papers, 2020 to 2023). Pulmonary arterial hypertension (PAH) is a group of diseases characterized by mean pulmonary artery pressure >20 mmHg and elevated pulmonary arterial resistance leading to right heart failure. "As such, recent research data has identified IL-32 as a potential new biomarker of pulmonary arterial hypertension and an association with CAD has also been shown." (PMID 36769623, 2023). "IL-32 has been tested as a biomarker for detection of pulmonary arterial hypertension (PAH) in patients with SSc." (PMID 36875066, 2023). "In keeping with this, increased IL32 staining was observed in tissue sections from patients with pulmonary hypertension, whereas in cellular models, IL32 silencing decreased endothelial cells proliferation and the expression of the adhesion molecule ICAM-1." (PMID 37108628, 2023). "Endothelial cells, present in the plexiform lesions of pulmonary vasculature of patients with idiopathic pulmonary hypertension, express IL-32, which is likely involved in the proliferation and activation of these abnormal endothelial cells." (PMID 37762689, 2023). "Indeed, in patients affected by systemic sclerosis, circulating IL32 levels were higher in those with than those without pulmonary arterial hypertension." (PMID 37108628, 2023).
cutaneous T-cell lymphoma (4 papers, 2021 to 2023). "IL-32 was further reported to be associated with the occurrence and development of various malignant tumors such as gastric cancer, lung cancer, and cutaneous T-cell lymphoma, suggesting it has a critical role in tumor development." (PMID 34414188, 2021). "IL32 was reported to accelerates the proliferation of cutaneous T-cell lymphoma cell lines through mitogen-activated protein kinase (MAPK) and NF-κB signaling pathways." (PMID 36417130, 2023). "A recent report noted that IL-32 acted as an essential growth factor for human cutaneous T-cell lymphoma cells." (PMID 34414188, 2021). "Higher expression of IL-32 was found to be associated with more proliferative and progression in the following cancers, AML, cutaneous T-cell lymphoma (CTCL), gastric B-cell lymphoma (GBCL), multiple myeloma (MM), HCC, and breast, lung, colon, pancreatic, gastric, and esophageal cancers." (PMID 35281008, 2022). "IL32 exerted both anti-tumor or pro-tumor effects in a cancer type dependent manner and it has been reported to play a role in the formation and maintenance of lesions in cutaneous T-cell lymphoma (CTCL)." (PMID 36417130, 2023).
HCMV infection (4 papers, 2013 to 2025). "IL-32 protein expression levels at different time points following HCMV infection were measured by western blot analysis." (PMID 23402302, 2013). "In this study, we validated that expression of IL-32 was activated by active HCMV infection and functionally down-regulated by ectopically expressed hcmv-miR-UL112-1 in HEK293 cells." (PMID 23402302, 2013). "Detailed kinetics of the transcription of IL-32 mRNA and expression of IL-32 protein during human cytomegalovirus (HCMV) infection were determined by semi-quantitative RT-PCR and western blot, respectively." (PMID 23402302, 2013). "HCMV infection activated cellular IL-32 transcription mainly in the immediately early (IE) phase and elevated IL-32 protein levels between 6 and 72 hours post infection (hpi) in the human embryonic lung fibroblast cell line, MRC-5." (PMID 23402302, 2013). "IL-32 levels in the sera of patients with active HCMV infection were significantly higher than those in the HCMV IgM negative control group (F=23.957, P<0.001)." (PMID 23402302, 2013). "HCMV infection can induce the expression of IL-32 at both the mRNA and protein levels in HCMV-infected MRC-5 cells." (PMID 23402302, 2013). "Interestingly, human cytomegalovirus (HCMV)-encoded miRs, namely, miR-UL112-1, can also reduce both mRNA and IL-32 protein levels in HEK293 by targeting the 3’-UTR of IL-32 mRNA following HCMV infection." (PMID 41383621, 2025). "In summary, IL-32 expression in active HCMV infection was firstly investigated in our study." (PMID 23402302, 2013). "It is hypothesized that certain pathways might be activated to down-regulate or block the expression of IL-32 during HCMV infection." (PMID 23402302, 2013). "IL-32 expression was induced by active HCMV infection and could be functionally down-regulated by ectopically expressed hcmv-miR-UL112-1." (PMID 23402302, 2013). "Mean IL-32 levels in the sera of patients with active HCMV infection were 4.1778±1.1663 ng/ml." (PMID 23402302, 2013). "In the present study, the expression levels of IL-32 were compared among serum samples from patients with active HCMV infection and samples from HCMV-IgM negative individuals." (PMID 23402302, 2013). "IL-32 protein levels were measured in the sera of 40 patients with active HCMV infections (HCMV IgM positive) and 32 HCMV IgM negative control individuals by enzyme-linked immunosorbent assays (ELISA)." (PMID 23402302, 2013). "Serum levels of IL-32 in HCMV-IgM positive patients (indicating an active HCMV infection) were significantly higher than those in HCMV-IgM negative controls." (PMID 23402302, 2013). "In addition, functional down-regulation of IL-32 by hcmv-miR-UL112-1 was detected in transfected human embryonic kidney (HEK293) cells, and the effect of hcmv-miR-UL112-1 on IL-32 during HCMV infection was primarily discussed." (PMID 23402302, 2013). "The adaptive-like NK cells featured high expression of CD3E, LAG3, and IL-32 with no expression of FCER1G and TCRs, consistent with published scRNA-seq data (except for low expression of KLRC2/NKG2C, the canonical markers for adaptive NK cells after human cytomegalovirus (HCMV) infection) 21,22." (PMID 40394087, 2025).
Hypertension (4 papers, 2022 to 2024). The presence of chronic increased pressure in the systemic arterial system. "In this cohort characterized by a high prevalence of hypertension, the association was mainly explained by the link between IL32 and systolic blood pressure levels, but we also observed a non-significant trend for association with diastolic blood pressure levels." (PMID 37108628, 2023). "The underlying hypothesis was that IL32 may bridge hepatic fat accumulation and lipotoxicity with endothelial activation and development of arterial hypertension." (PMID 37108628, 2023). "In addition, IL32 was also implicated in the pathogenesis of pre-eclampsia, whose hallmark is the development of arterial hypertension during pregnancy." (PMID 37108628, 2023). "In this respect, IL32 may play a role in endothelial cell function, and in the activation and proliferation associated wtith vasocontrisction and development of arterial hypertension." (PMID 37108628, 2023). "We preliminarily evaluated the distribution of fasting circulating IL32 in the Liver-Bible-2021 cohort of apparently healthy middle-aged individuals with metabolic dysfunction, about two thirds of whom were affected by arterial hypertension." (PMID 37108628, 2023). "After adjustment for possible confounders (abdominal circumference and arterial hypertension) only ACE-I and diuretics remained independently associated with lower IL32 (p < 0.05)." (PMID 37108628, 2023). "However, further studies are required to confirm these findings and to clarify the mechanism linking IL32 release, inflammation and hypertension." (PMID 37108628, 2023). "Furthermore, IL32 may be involved in the pathogenesis of hypertension and possibly of the meta-inflammation leading to the progression of cardiovascular disease and its complications." (PMID 37108628, 2023). "However, studies that directly address the role of IL32 signaling in the pathogenesis of hypertension are lacking." (PMID 37108628, 2023).
Insulin resistance (4 papers, 2023 to 2025). Increased resistance towards insulin, that is, diminished effectiveness of insulin in reducing blood glucose levels. "Recent studies have correlated IL-32 with non-alcoholic fatty liver disease activity score (NAS), insulin resistance and aminotransferase levels, suggesting a close association with MASLD20,21." (PMID 39939782, 2025).
lung diseases (4 papers, 2018 to 2022). "IL-32, previously considered a pro-inflammatory cytokine, is a multifunctional protein with a potential role in lung diseases." (PMID 30257681, 2018).
periodontitis (4 papers, 2019 to 2022). An acute or chronic inflammatory process that affects the tissues that surround and support the teeth. "Genome-wide analysis of gene expression showed that 53 transcripts were differentially expressed in periodontitis subjects in comparison to healthy controls, with 1 transcript (interleukin-32 [IL32]) being differentially decreased." (PMID 36233348, 2022). "The levels TNF-α and IL-32 in gingival crevicular fluid and saliva were higher in chronic periodontitis patients, and then after treatments, these two biomarkers decreased." (PMID 33383828, 2020).
systemic sclerosis (4 papers, 2020 to 2025). A chronic disorder, possibly autoimmune, marked by excessive production of collagen which results in hardening and thickening of body tissues. "Unlike NL-specific fibroblasts, these systemic sclerosis-enriched fibroblast clusters did not overexpress IL32, CCL5, or CXCL9." (PMID 39989459, 2025).
thyroid cancer (4 papers, 2016 to 2021). "IL-32 protein was expressed higher in thyroid cancer tissues." (PMID 32655554, 2020). "The effect of Isoginkgetin on splicing was also evaluated by studying the expression of interleukin 32 (IL-32) alternative isoforms, where IL-32γ isoform is overexpressed upon the treatment, correlating with cell death in cell lines derived from thyroid cancer." (PMID 27610372, 2016). "However, the level of IL32 mRNA expression was higher in normal tissues than in tumor tissues of kidney chromophobe (KICH) and thyroid carcinoma (THCA), as indicated in green." (PMID 34682815, 2021). "Although previous research showed that IL-32 is expressed in differentiated thyroid cancer (TC) cells, the role of IL-32 in TC cell migration has not been investigated." (PMID 31201646, 2019).
allergic asthma (3 papers, 2017 to 2018). A asthma with a basis in a pathological type I hypersensitivity reaction. "The anti-inflammatory property of IL-32 has been demonstrated in a murine ovalbumin (OVA) model of allergic asthma." (PMID 29940981, 2018). "Of particular note was the observation of the anti-inflammatory property of IL-32 in a murine ovalbumin model of allergic asthma." (PMID 29940981, 2018). "In allergic asthma, Rhinovirus infection could induce the expressions of the inflammation-related genes and IL-32." (PMID 29940981, 2018).
ankylosing spondylitis (3 papers, 2022 to 2023). An autoimmune chronic inflammatory disorder characterized by inflammation in the vertebral joints of the spine and sacroiliac joints. "IL-32 increases bone resorption but also appears to be responsible for excessive bone formation seen in ankylosing spondylitis." (PMID 35307770, 2022).
chronic hepatitis B (3 papers, 2015 to 2025). "In non-alcoholic steatohepatitis and chronic hepatitis B, hepatic IL-32 expression is also increased." (PMID 40149726, 2025). "Hepatic expressions of B7-H6 and interleukin-32 (IL-32) were examined by immunochemistry staining in samples from patients with HBV-ACLF or mild chronic hepatitis B (CHB)." (PMID 26241657, 2015).
chronic rhinosinusitis (3 papers, 2014 to 2022). Chronic form of sinusitis. "IL-32 was recently described as a proinflammtory factor involved in many inflammatory disorders such as chronic rhinosinusitis, a condition mostly caused by gram positive bacteria infection." (PMID 24633341, 2014).
colitis (3 papers, 2006 to 2025). Inflammation of the colon. "We therefore conclude that IL-32 is closely associated with TNFα, and contributes to the exacerbation of TNFα-related inflammatory arthritis and colitis." (PMID 17078892, 2006). "In vivo expressed IL-32 was therefore supposed to play an important role in the exacerbation of colitis, in part through the TNFα-inducing effect." (PMID 17078892, 2006).
coronary artery stenosis (3 papers, 2022 to 2024). "We aimed to evaluate the association between IL‐32 levels and coronary stenosis severity, IL‐32 polymorphisms rs28372698 and rs4786370, and CAD susceptibility." (PMID 34799941, 2022). "We also suggest that plasma IL‐32 levels may be indicative of coronary artery stenosis and the efficacy of PCI and provide guidance for risk stratification and disease management." (PMID 34799941, 2022). "We further assessed the use of IL‐32 levels to predict coronary stenosis severity (Gensini scores and diseased coronary vessels)." (PMID 34799941, 2022). "IL‐32 levels were significantly different at different levels of coronary artery stenosis (p < 0.05), and logIL‐32 was positively correlated with the Gensini score (r = 0.357, p < 0.01)." (PMID 34799941, 2022). "However, studies investigating the relationship between IL‐32 levels and coronary stenosis are rare in patients with CAD, and the role of rs28372698 and rs4786370 in CAD susceptibility has not yet been reported." (PMID 34799941, 2022). "We further assessed the effect of IL‐32 SNPs on coronary stenosis severity." (PMID 34799941, 2022). "Our study showed that plasma IL‐32 levels are closely correlated with the degree of coronary artery stenosis and suggests that IL‐32 may be an independent predictor of CAD." (PMID 34799941, 2022). "We suggest that IL‐32 levels can be a simple and readily available inflammatory marker to predict CAD and assess coronary artery stenosis." (PMID 34799941, 2022). "Moreover, it also shows significantly increased plasma IL‐32 levels in patients with CAD and its positive correlation with coronary artery stenosis." (PMID 34799941, 2022). "However, both SNPs had no obvious effect on IL‐32 levels or coronary stenosis severity in patients with CAD." (PMID 34799941, 2022). "Besides, the predictive ability of IL‐32 for the long‐term prognosis and progression of coronary stenosis was not examined because of the cross‐sectional design of our study; therefore, future follow‐up investigations are necessary." (PMID 34799941, 2022).
endometrial cancer (3 papers, 2020 to 2025). Primary or metastatic malignant neoplasm involving the endometrium (mucous membrane that lines the endometrial cavity). "In current study, we found that PHF6 affected the CDK4 and IL32 expression through transcriptional regulation in endometrial carcinoma cells." (PMID 36756714, 2023). "We found that PHF6 KD significantly increased the mRNA expression of IL12 and IL32 in endometrial carcinoma cells." (PMID 36756714, 2023). "While knockdown of PHF6 in endometrial carcinoma cells increased T‐cell migration by promoting IL32 production and secretion." (PMID 36756714, 2023). "Additionally, PHF6 knockout enhanced T cell migration by increasing IL32 production and secretion in endometrial cancer cells." (PMID 41515604, 2025).
fatty liver disease (3 papers, 2022 to 2024). A reversible condition wherein large vacuoles of triglyceride fat accumulate in liver cells via the process of steatosis. "Consistently, a common IL32 genetic variant associates with lower indices of liver damage and lower hepatic steatosis in humans." (PMID 38232700, 2024). "Consistently, we identified a genetic variant in IL32 (rs76580947) that reduces the circulating levels of this cytokine and protect against liver steatosis in three independent study cohorts." (PMID 38232700, 2024). "Taken all this together, these data are consistent with the in vitro experiments that decreasing IL-32 level may be beneficial against liver steatosis and fibrosis in individuals at risk for SLD." (PMID 38232700, 2024). "We recently identified Interleukin-32 (IL32) as the most upregulated transcript in the liver of obese individuals with severe fatty liver disease, namely, with steatohepatitis and/or clinically significant fibrosis." (PMID 37108628, 2023). "The association of altered blood pressure control with IL32 was present both in participants with and without fatty liver." (PMID 37108628, 2023). "Fatty liver disease is most frequently related to metabolic dysfunction (MAFLD) and associated comorbidities, heightening the risk of cardiovascular disease, and is associated with higher hepatic production of IL32, a cytokine linked with lipotoxicity and endothelial activation." (PMID 37108628, 2023). "The authors concluded that when IL-32 is overexpressed, independent of PNPLA3 genotype, it significantly correlated with increased hepatic steatosis and significant fibrosis." (PMID 35036892, 2022).
gastritis (3 papers, 2014 to 2025). Inflammation of the stomach. "However, the association between IL-32 expression and H. pylori-induced gastritis and its exact regulation mechanism including whether auto−/paracrine effects on the expression of IL-32 may be involved in the process was remain unknown." (PMID 24633341, 2014). "Gastric IL-32 mRNA and protein expression were elevated in patients with H. pylori infection and positively correlated with gastritis." (PMID 24633341, 2014). "To study whether IL-32 is involved in the pathogenesis of H. pylori induced gastritis, we first determined the IL-32 mRNA expression in gastric biopsy specimens from subjects with and without H. pylori infection." (PMID 24633341, 2014). "To evaluate whether the expression of IL-32 was related to the degree of inflammation in H. pylori-infected gastric samples, we divided the samples into normal and mild, moderate and severe gastritis groups based on histology assessment as described in Materials and Methods." (PMID 24633341, 2014). "Our results showed that IL-32 might be involved in the pathogenesis of H. pylori-related gastritis." (PMID 24633341, 2014). "IL-32 level is elevated in patients with H. pylori infection and its expression is regulated by proinflammatory stimuli, suggesting that IL-32 may play a role in the pathogenesis of H. pylori-related gastritis." (PMID 24633341, 2014). "In addition, the semi-quantitative evaluation of IL-32 immunoreactivity confirmed that the expression of IL-32 in gastric tissues of H. pylori-infected patients at protein level was also significantly increased compared with those in H. pylori–negative gastric tissues and in mild gastritis." (PMID 24633341, 2014).
granulomatosis with polyangiitis (3 papers, 2018 to 2023). A small-vessel necrotizing vasculitis characterized by the association of inflammation of the vessel wall and peri- and extravascular granulomatosis. "IL32 involvement has been described in vasculitides such as granulomatosis with polyangiitis and anti-neutrophil cytoplasm antibodies (ANCA) associated vasculitis." (PMID 30037347, 2018).